FOXM1 (forkhead box M1)
Diseases named in the same sentence as FOXM1 in open-access papers (continued):
Sharing a sentence is not in itself a finding about the gene and the disease.
breast cancer (continued). "In agreement with our expression data, functional studies revealed exogenous expression of ERBB2 in ERBB2-negative breast cancer cells (MCF7 and T47D) to enhance the expression of FOXM1 and MMP2." (PMID 31620367, 2019). "These genes include AURKB, BUB1, CHEK1, FOXM1, KIFC1, and TTK7, five of which, BUB1, CHEK1, FOXM1, KIFC1, and TTK, we have also identified and have functionally validated to have a selective requirement for cell growth in breast cancer cell models." (PMID 29535384, 2018). "Accordingly, paclitaxel has been shown to target the expression of FOXM1 and its downstream target the kinesin KIF20A, to drive abnormal mitotic spindle formation, mitotic catastrophe and senescence in breast cancer cells." (PMID 29540677, 2018). "Here, we explored the expression profile and prognostic values of FoxM1 based on analysis of pooled clinical datasets derived from online accessible databases, including ONCOMINE, Breast Cancer Gene-Expression Miner v4.0, and Kaplan-Meier plotter." (PMID 29416660, 2018). "CEP55 (55 kDa) is a centrosomal protein involved in cytokinesis and a known downstream target of FOXM1 oncogene in HNSCC and breast cancer." (PMID 30008265, 2018). "Depletion of FOXM1, accompanied by repressed NBS1 expression and reduced ATM activation, can render parental MCF-7 breast cancer cells and MCF-7 epirubicin resistant cells more sensitive to epirubicin-induced cellular senescence." (PMID 29180117, 2018). "We found that breast cancer subtypes could be assigned with >90% diagnostic accuracy, as indicated by the area under the ROC curve of the partition tree, by differential expression analysis with respect to a normal breast tissue reference using only 4 genes: CBX7, ESR1, FOXC1, and FOXM1." (PMID 29868123, 2018). "For instance, in epirubicin-resistant breast cancer and in ovarian cancer, OTUB1 catalyzes the cleavage of the K48-specific ubiquitin linkage from FOXM1, which promotes cancer progression via facilitating cell proliferation and drug resistance." (PMID 30208972, 2018). "Like FOXM1, overexpressed NSB1 has also been observed in MCF-7 epirubicin resistant cells and breast cancer patients with poorer outcome." (PMID 29180117, 2018). "In concordance, there is a positive correlation between ERα and FOXM1, and an inverse correlation between ERα and FOXO3 in breast cancer patients." (PMID 29180117, 2018). "That possibility is supported by our observations that FoxM1 inhibits expression of the differentiation genes GATA3 and FoxA1 in breast cancer cells." (PMID 28387346, 2017). "Our studies are the first to report activation of IGF-1R-FoxM1 as a mechanism of invasion in GDF15-overexpressing breast cancers, providing rationale for preclinical evaluation of treatments that co-target IGF-1R and FoxM1." (PMID 29212236, 2017). "FOXM1 is a transcription factor known to upregulate MELK in basal-like breast cancers and MELK inhibition has been reported to downregulate FOXM1 in other cancers." (PMID 28235006, 2017). "Our results on breast cancer cells are in line with that observations and directly link SLPI expression to regulation of FoxM1 function." (PMID 29312532, 2017). "What is interesting is that some researchers reported that there is a positive regulatory feedback loop between FoxM1 and the PDGF/Akt signaling pathway, and the loop promotes breast cancer tumorigenesis." (PMID 28784180, 2017). "Nevertheless, the results of multivariate Cox regression model suggested that the activity of FOXM1 in MDA-MB-231 cell line, proliferation activity, still is an independent biomarker in breast cancer sample prognosis." (PMID 29100329, 2017). "In the current study, we demonstrate that GDF15 promotes EMT and invasiveness of breast cancers through insulin-like growth factor-1 receptor (IGF-1R) signaling and transcription factor FoxM1 upregulation." (PMID 29212236, 2017).
breast cancer (continued). "BIRC5 and FOXM1 downregulation and IL24 induction was also evident in breast cancer patient datasets following taxane treatment." (PMID 28187446, 2017). "To gain insight in regulation of mitotic kinesin expression in breast cancer cell lines by MMB and FOXM1, we performed chromatin immunoprecipitation (ChIP) assays in MDA-MB-231 breast cancer cells." (PMID 28061449, 2017). "The significance of both FOXM1 and KIF20A in survival analyses provides further evidence for the involvement of both genes in breast cancer progression and drug response." (PMID 25961928, 2016). "The physiological relevance of RNF168-mediated FOXM1 repression is further emphasized by the significant inverse correlation between FOXM1 and RNF168 expression in breast cancer patient samples." (PMID 27526106, 2016). "The physiological relevance of the regulation of FOXM1 by RNF168 is further underscored by the significant inverse correlation between FOXM1 and RNF168 in breast cancer patient samples." (PMID 27526106, 2016). "Our data, for the first time, defined a role for miR-671-5p as a tumor suppressor miRNA in breast cancer, involving cell proliferation, invasion, cell cycle arrest, EMT, and chemotherapeutic sensitivity by directly targeting FOXM1 and its downstream genes." (PMID 26588055, 2016). "The results showed that RNF168 interacted with FOXM1, suggesting that FOXM1 and RNF168 form complexes in breast cancer cells both in the absence and in the presence of epirubicin." (PMID 27526106, 2016). "In agreement, depletion of FOXM1 by siRNA downregulates KIF20A expression and paclitaxel downregulates FOXM1 and therefore, KIF20A expression in MCF-7 breast cancer cell lines." (PMID 25961928, 2016). "We next tested the effects of targeting FOXM1 and KIF20A in MCF-7 and the paclitaxel-resistant MCF-7 TaxR breast cancer cell lines." (PMID 25961928, 2016). "The physiological relevance of the regulation of FOXM1 by OTUB1 is further underscored by the significant correlations between FOXM1 and OTUB1 expression in breast cancer patient samples." (PMID 26148240, 2016). "The physiological relevance of the regulation of KIF20A by FOXM1 is further highlighted by the strong and significant correlations between FOXM1 and KIF20A expression in breast cancer patient samples." (PMID 25961928, 2016). "Triple negative breast cancer (TNBC) cells (MDA-MB-231, BT-20) had higher FOXM1 expression than other breast cancer cell lines, including the ER-positive T-47D, and ZR-75.1 cells and the HER2/Neu-positive SKBR3 cells." (PMID 26918606, 2016). "Similar to FOXM1, KIF20A expression is downregulated by paclitaxel in the sensitive MCF-7 breast cancer cells and deregulated in the paclitaxel-resistant MCF-7TaxR cells." (PMID 25961928, 2016). "Our study supports the notion that FoxM1 overexpression, upregulation of PDGF-A, and activation of the PI3K/AKT pathway favor breast cancer cell proliferation and tumorigenesis." (PMID 25869208, 2015). "Our study demonstrates a novel positive regulatory feedback loop between FoxM1 and the PDGF/AKT signaling pathway; this loop contributes to breast cancer cell growth and tumorigenesis." (PMID 25869208, 2015). "We therefore analyzed the correlation of FoxM1 with PDGF-A in different breast cancer cell lines and found that PDGF-A expression level was positively correlated with FoxM1 in these cell lines." (PMID 25869208, 2015). "However, the mechanisms for the roles of FoxM1 in breast cancer are largely unknown." (PMID 25869208, 2015). "Our results demonstrate that PDGF-A is a direct transcriptional target of FoxM1 and that the expression of FoxM1 is significantly correlated with that of PDGF-A in breast cancer." (PMID 25869208, 2015). "In support of a mechanistic role of EMT in tamoxifen resistance of breast cancer cells, over-expression of Pin-1, AKT, Nicastrin and Notch4, FoxM1, brachyury as well as modulation of several microRNAs has been reported." (PMID 26206152, 2015).
breast cancer (continued). "Together, these results suggest that FoxM1 activated the PDGF/AKT signaling pathway and promoted breast cancer cell growth." (PMID 25869208, 2015). "Since FoxM1 and the PDGF/AKT signaling pathway are both dysregulated in breast cancer and since both play important roles in breast tumorigenesis, in this study we explored the relationship between them to elucidate the responsible molecular mechanisms." (PMID 25869208, 2015). "Taken together, these results indicate that FoxM1 activated the AKT signaling pathway and promoted breast cancer cell growth through PDGF-A." (PMID 25869208, 2015). "In summary, our findings show crosstalk between FoxM1 and the PDGF/AKT signaling pathway in human breast cancer." (PMID 25869208, 2015). "We also found that the PDGF/AKT pathway elevates FoxM1 expression and that the level of FoxM1 is significantly correlated with that of PDGF-A and with the activity of the AKT pathway in human breast cancers." (PMID 25869208, 2015). "We experimentally validated the expression of FOXM1 and AURKB in 42 breast brain metastasis samples (which included those used in the expression arrays) and in a series of 50 primary breast cancer samples by qRT-PCR." (PMID 24489661, 2014). "Similar functions of FoxM1 in stimulating expression of MMP-2 and MMP-9 have also been documented in other malignancies, such as glioblastoma, breast carcinoma, and colorectal carcinoma." (PMID 23006512, 2012). "Thus FOXM1 inhibitors could represent useful new anticancer therapeutics for breast cancer as well." (PMID 18254960, 2008). "A positive correlation between FOXM1 and TOP2A expression was found in patients with breast cancer undergoing EC-T chemotherapy, both negatively correlated with STUB1, whose higher expression levels were linked to increased pathologic complete response (pCR) rates." (PMID 41851614, 2026). "Overexpression of FOXM1 could upregulate UBE2C expression at the mRNA level and protein levels in breast cancer cells." (PMID 40729680, 2025). "This study aimed to evaluate the prognostic significance of FOXM1 expression specifically in hormone receptor-positive, HER2-negative (HR+HER2-) breast cancer patients with high KPNA2 expression, and to identify potential FOXM1-targeted therapeutic strategies for this patient subgroup." (PMID 40002266, 2025). "This relationship manifests in more aggressive tumor characteristics, including larger tumor size, increased lymph vascular invasion, and higher rates of metastasis, with high FOXM1 expression correlating with poorer clinical outcomes and increased recurrence rates in HER2-positive breast cancers." (PMID 40002266, 2025). "However following FOXM1 expression as a biomarker to gain insights into dependence on, and resistance to PI3K/AKT pathway inhibition in ER+ PIK3CA mutant breast cancer is important." (PMID 40263319, 2025). "Furthermore, FOXM1 can upregulate USP39, therefore forming a positive feedback loop that promotes breast cancer cell proliferation." (PMID 40003882, 2025). "Notably, HR+/HER2- breast cancer patients with high KPNA2 but low FOXM1 mRNA levels showed significantly better survival outcomes (OS: p = 0.0355; DSS: p = 0.0424), suggesting a novel prognostic signature for this major breast cancer subtype." (PMID 40002266, 2025). "Notably, the regulation of FoxM1 expression by USP39 has only been confirmed in cell lines of triple-negative and estrogen receptor (ER)-positive breast cancer subtypes." (PMID 40672756, 2025). "However, a study using a PROTAC degrader of FOXM1 revealed decreased GLUT1 expression in hepatocellular carcinoma and breast cancer models." (PMID 40713647, 2025). "We suggested that CDCA5 promoted progression of breast cancer via CDCA5/FOXM1/Wnt axis, CDCA5 might serve as a novel therapeutic target for breast cancer treatment." (PMID 38978058, 2024). "We also verified the negative correlation of FOXO3 and FOXM1 by Breast Cancer Gene-Expression Miner v4.9 (P < 0.01)." (PMID 37976368, 2024).
breast cancer (continued). "Importantly, FOXM1 is a potential therapeutic target, particularly in HER2+ breast cancers that are resistant to HER2-targeted therapies." (PMID 39594778, 2024). "Forkhead box M1 (FOXM1), which along with AURKA is a co‐predictor of prognosis and sorafenib efficacy in HCC, regulates AURKA at the promoter level resulting in increased self‐renewal capacity of breast cancer stem cells." (PMID 38590119, 2024). "Inhibition of FOXM1 following siRNA treatment reverses cisplatin resistance in MCF-7-CISR breast cancer cells, suggesting that FOXM1 is a potential therapeutic target in cisplatin-resistant ER+ breast cancer." (PMID 39594778, 2024). "Our study provides additional support for the involvement of FOXM1 in macrophage infiltration and polarization in the context of breast cancer, particularly between TNBC and non-TNBC." (PMID 39834541, 2024). "Among these, FOXM1 stood out due to its significant differential expression in breast cancer tissues between TNBC and non-TNBC, being notably upregulated in TNBC samples." (PMID 39834541, 2024). "In addition, we found that the E2F1 was recruited to the FOXM1 promoter region, indicating that CDCA5 was capable to affect FOXM1 expression via binding to E2F1, thereby promoting in the progression of breast cancer." (PMID 38978058, 2024). "E2F4, FOXM1, and E2F1 are all indicated in development and progression of breast cancer." (PMID 38886591, 2024). "Similarly, FOXM1 regulates cell migration and invasion via MMP-2 and MMP-9 in tumors such as glioblastoma, colorectal carcinoma, and breast carcinoma." (PMID 39594778, 2024). "Indeed, western blotting analysis revealed a significant reduction in the protein expression of FoxM1, a critical transcription factor for ITGB1 expression 27, in USP22-null breast cancer cells." (PMID 37398311, 2023). "Supporting the specificity of FOXM1 inhibitors, they did not alter the expression of FOXA1, a forkhead protein implicated in luminal breast cancers." (PMID 36795481, 2023). "Collectively, our study identified USP22 as a FoxM1-specific deubiquitinase which promotes FoxM1 transcriptional activation for ITGB1 expression, which consequently promotes breast cancer stem cell self-renewal and drives breast cancer metastasis to distal organs including lung." (PMID 37398311, 2023). "Likewise, we have shown the combined effectiveness of our FOXM1 inhibitors with the CDK4/6 inhibitors palbociclib, ribociclib and abemaciclib in ER-containing breast cancer cells." (PMID 37370117, 2023). "Another study revealed that H3K79 demethylation by DOT1Li could reduce forkhead box M1 (FOXM1) expression and increase IL-12 production, thus promoting DCs maturation in breast cancer." (PMID 37273004, 2023). "Additionally, miR-4521-mediated FOXM1 downregulation perturbs cell proliferation, invasion, cell cycle progression, and epithelial-to-mesenchymal progression (EMT) in breast cancer." (PMID 37025658, 2023). "This would likely include breast cancer, hepatocellular carcinoma, and prostate cancer, to name a few, and possibly MPNST, if future investigations verify our prediction based on mounting evidence that FOXM1 is a critical mediator of its pathogenesis." (PMID 37686402, 2023). "In addition, FOXM1 regulates downstream proteins, including survivin, RAD51, which contribute to homologous recombination DNA repair in breast cancer cells and, cyclin B1, a cell cycle regulatory protein." (PMID 37242455, 2023). "Real-time PCR analysis and immunohistochemical staining both demonstrate the higher transcription levels of the FOXM1 gene in mammary tumor tissues, as opposed to normal breast tissues." (PMID 37626655, 2023). "FOXM1, a forkhead family of transcription factor, is involved in the regulation of cell proliferation and mitosis by regulating transcription of p27kip1, cyclin D1, cdc25, KIF20A, and CENP-A in breast cancer." (PMID 37025658, 2023).
breast cancer (continued). "The success of combination therapy in hormone receptor-positive and HER2-expressing breast cancers, and the clear need for better therapy options in TNBC, provide a strong rationale for continued study of the use of FOXM1 inhibitors in combination with other drugs." (PMID 37370117, 2023). "Indeed, reconstitution of FoxM1 expression fully restored the endogenous integrin b1 expression in both USP22-null 4T1 and L2G+ TN1 breast cancer cells as determined by western blotting and qRT-PCR, which was further confirmed by flow cytometry." (PMID 37398311, 2023). "Since SFKi may affect PyVmT tyrosine phosphorylation, we treated the human luminal breast cancer cell line MCF7 and observed a similar effect on proliferation, as well as reduced FOXM1 expression, when SFKs were inhibited." (PMID 36795481, 2023). "As an autonomous feature of estrogen concentrations, the reduced levels of FOXM1 abate the propagation of mammary tumor cells without alleviating cell death." (PMID 37626655, 2023). "While FOXM1 was one of the genes downregulated when ERβ1 was exogenously expressed in breast cancer cells, it was not affected by ERβ1 overexpression in another study." (PMID 35267428, 2022). "In similar, MTX, Etoposide, Fulvestrant, and Resveratrol could suppress the expression of FOXD1, FOXA1, FOXM1, and FOXP1, respectively, which exhibited oncogenic potential in LGG, PRCA/breast cancer, LUAD/LUSC, and PAAD." (PMID 36292640, 2022). "FDI-6 has been identified as a FOXM1-specific inhibitor in breast cancer cells by blocking the DNA binding activity of FOXM1, and its effect is selective for FOXM1 target genes without affecting genes regulated by homologous forkhead family factors." (PMID 36291764, 2022). "TCGA analysis showed a significant increase in the relative expression of FOXM1 in All, Luminal A, and unclassified (or that failed to classify) breast cancers for NHB, and a significant increase of relative expression in Her2 for NHW." (PMID 36494865, 2022). "In addition, a previous study reported that FOXM1 not only promoted breast cancer progression and metastasis through EMT but also mediated PI3Kα inhibitor resistance in ER+ breast cancer." (PMID 35197112, 2022). "In breast cancer, RUNX2 and FOXM1 induce EMT and are regulated by sumoylation, and they share DNA binding sites in ERα; this association leads to the activation of genes involved in proliferation and metastasis and the development of endocrine resistance during tamoxifen treatment." (PMID 36551878, 2022). "We found that CTCs are resistant to ERα inhibition, and that HER2 is required for sustained FOXM1 expression even in ER+ breast cancer cells that do not have HER2 amplification or activating HER2 mutations." (PMID 33920089, 2021). "Our findings from the current study are concordant with our previously published work on transcription factors such as ERBB2, RABL6, FOXM1 and MITF which are most effected by palbociclib treatment in MDA-MB-231 breast cancer cells, reducing colony formation, cell migration and viability." (PMID 34565361, 2021). "Targeting of NFkB and FOXM1 might therefore allow endocrine treatment resistance to be circumvented and might be beneficial for the treatment of metastatic ER+/HER2− breast cancer." (PMID 33920089, 2021). "In breast cancer cells, SIRT1 was found to deacetylase mitogen-activated protein kinase 1 (MAP2K1), leading to inactivation of the MEK/ERK cell signaling pathway and reduction in FOXM1 protein." (PMID 34680943, 2021). "On the other hand, lots of TFs, like EN1, STAT3, SOX9, and FOXM1, showed essential oncogenic functions in non-luminal breast cancer." (PMID 34249704, 2021). "It was identified that silencing of miR-193a-3p through hypermethylation can promote HER2 positive breast cancer progress by targeting growth factor receptor bound protein 7 (GRB7), extracellular signal-regulated kinase 1/2 (ERK1/2), and forkhead box M1 (FOXM1) signaling." (PMID 33628829, 2021).